STAT3 (signal transducer and activator of transcription 3)
Diseases named in the same sentence as STAT3 in open-access papers (continued):
Sharing a sentence is not in itself a finding about the gene and the disease.
cancer (continued). "Our results demonstrate the utility of blocking intracellular STAT3 signaling upon targeting of the therapeutically unexplored CC domain of STAT3 and pave a way towards inhibitory strategies in diverse diseases including cancer and autoimmune disorders." (PMID 32807795, 2020). "A recent study has shown that interleukin-6 (IL-6)-mediated STAT3 phosphorylation plays a role in EndMT, thus inducing cancer growth." (PMID 32296578, 2020). "This induces STAT3 dimerization and translocation to the nucleus, where STAT3 dimers activate cancer-related genes including Myc, Bcl-2, and Survivin28,29." (PMID 32528731, 2020). "The STAT3 signaling pathway is oncogenic and frequently over-activated in various human cancer types, including HCC." (PMID 33222697, 2020). "Amongst the genes directly regulated by STAiR18 and STAT3 we identified several targets involved in cell cycle progression and cancer cell survival, like the protein tyrosine phosphatase type 4 member 1 (PTP4A1) and the transmembrane protein 45A (TMEM45A)." (PMID 32041604, 2020). "Many of the STAT3-induced genes are cytokines and growth factors, which again bind to their receptors and activate STAT3 thereby maintaining chronic STAT3 activation in many cancers." (PMID 33182552, 2020). "In contrast to the transient phosphorylation of STAT3 observed under physiological conditions of normal cells, STAT3 often persistently activates in many cancers and in many human cancer models." (PMID 31949488, 2020). "Stat3, which can be triggered by cytokines and growth factors, is persistently activated in many types of cancer." (PMID 31778258, 2020). "In cancer cells, constitutive activation of STAT3 is necessary for promoting the overexpression of genes that encode anti-apoptotic proteins and that are regulators of cell cycle and angiogenic factors." (PMID 33158194, 2020). "Such knowledge would be hoped to contribute to efforts to develop novel viral vaccines and, potentially, antivirals, as well as approaches for STAT3-related pathologies such as cancer." (PMID 32903273, 2020). "Apart from the known role of STAT3 in promoting cancer cell proliferation, invasion, and angiogenesis, STAT3 also showed the crucial role in immunosuppression." (PMID 32486001, 2020). "The activation of STAT3 also drives the deposition of extracellular matrix, which contributes to the initial anchoring and sustenance of metastatic cancer cells." (PMID 33322216, 2020). "Over the years, STAT3 has been shown to interact with several other transcription factors and signaling pathways at multiple levels to support cancer progression." (PMID 33335857, 2020). "Overall, these results suggest that STAT3‐driven MLST8 gene expression regulates cap‐dependent translation through 4E‐BP1 phosphorylation in cancer cells." (PMID 32495998, 2020). "Protein inhibitor of activated STAT (PIAS1) and suppressor of cytokine-signaling proteins 3 (SOCS3) negatively regulate STAT3 in cancer." (PMID 31900385, 2020). "In summary, small-molecule STAT3 inhibitors have antitumor activities and inhibit STAT3 phosphorylation but are yet to be approved for clinical cancer therapy." (PMID 32872659, 2020). "In this study, our data showed that leptin stimulated the phosphorylation of STAT3 and the translocation of p-STAT3 to the nucleus of cancer cells." (PMID 33371368, 2020). "Activated STAT3 can promote the transition to G1 phase and the process of cancer transformation by upregulating the expression of cyclin D1." (PMID 32382281, 2020). "By comparing cytotoxicity measured by the area under the curve (AUC) of 265 investigational and accepted compounds in pSTAT3 high and low cancer cell lines, we identified novel potential inhibitors of STAT3 activation." (PMID 32188095, 2020). "Here, our results clearly demonstrated that LINC00324 performed cancer-promoting actions through regulating the miR-769-5p/STAT3." (PMID 32369777, 2020).
cancer (continued). "It has also been demonstrated that the upregulation of TLR9 in glioma cancer stem-like cells is able to activate STAT3 and thus maintain the quiescent state of tumor-repopulating cells." (PMID 32984007, 2020). "Features representative of cancer stem cells show that higher expression of STAT3, AHR, and CCR2 modules distinguishes cancer stem-cell samples from their non–stem cancer cell counterparts." (PMID 32383980, 2020). "Based on this, understanding STAT3 related mechanisms, like regulating lipogenesis, was essential to understand cancer initiation and progression." (PMID 32486001, 2020). "A lowered expression of doxorubicin-induced STAT3 activation was found in the presence of β-caryophyllene in both cancer and normal cholangiocytes." (PMID 32252311, 2020). "The OSM-JAK-STAT pathway has been implicated in progression of several cancers, including NSCLC; treatment of NSCLC cells with filgotinib resulted in inhibition of STAT3 activation and reduced OSM receptor expression." (PMID 33521321, 2020). "The STAT3 signaling pathway is a well-known oncogene factor in different cancers, and its involvement in the malignancy and growth of GC cells has been extensively investigated." (PMID 32545648, 2020). "Though STAT3 is essential for survival during early embryogenesis, increased activation of STAT3 is often found in cancer cells, which, in turn, drives the downstream protein complexes to prolong survival." (PMID 32722030, 2020). "STAT3 can affect the Hsp70 promoter and increases its expression in cancer cells, mediating the upregulation of antiapoptotic proteins." (PMID 32733808, 2020). "For example, in doxorubicin-resistant TNBC cell inhibition of STAT3 activation by pharmacological inhibitor partly restored cancer cell sensitivity to the treatment, possibly through reduction in CSC proportion." (PMID 33585241, 2020). "The use of a targeting moiety for the selective silencing of STAT3 in cancer cells is thus imperative because it would permit to avoid the occurrence of severe side effects in normal tissues." (PMID 32486489, 2020). "Together this supports the concept that constitutive STAT3 activity is protecting cancer cells from apoptotic effects of mitotic inhibition." (PMID 32231398, 2020). "As the most important oncogenic downstream mediator of the JAK–STAT pathway, deregulated STAT3 has been demonstrated to promote cancer progression mainly through its role as transcription factor." (PMID 32041943, 2020). "In summary, we discover a new role of FBP1 in antagonizing STAT3-dependent expression of PD-L1 and the mechanism through which FBP1 loss in human cancer cells contributes to the upregulation of PD-L1 and resistance to anti-PD-L1 treatment." (PMID 31938049, 2020). "STAT3 plays important roles in the progression of various cancers by regulating the proliferation, invasion, angiogenesis and immune surveillance evasion." (PMID 32766155, 2020). "The IL-6/JAK/STAT3 pathway is overactivated in many cancer patients, and numerous studies involving preclinical in vitro and in vivo models have shown that targeting a single nodule in this pathway can have antitumor effects." (PMID 33363013, 2020). "In haematopoietic malignancies and solid tumours, the chronic inflammatory conditions and the maintenance of cancer stem cell properties are reported to be dependent on the IL-6/Stat3 axis, which also stimulates the self-renewal of neoplastic cells." (PMID 32467235, 2020). "The targeting of STAT3 signalling by resveratrol have demonstrated anti-cancer and antitumour activity in many cancers." (PMID 32731620, 2020). "Many studies have shown that inducing the inactivation of JAK2 can inhibit STAT3 activation and can thus inhibit STAT3 signaling, which then regulates apoptosis of cancer cells." (PMID 33330321, 2020).
cancer (continued). "It has recently been found that SHP2 can play a dual role in the different signaling pathways associated with the development of cancer; for example, SHP2 has a negative regulatory effect on the JAK/STAT3 signaling pathway." (PMID 33076315, 2020). "Regarding the fact STAT3 is involved in numerous processes, its importance has been particularly accepted in the development of cancer." (PMID 32722030, 2020). "A summary of pre-clinical studies in which STAT3-targeted compounds are used to enhance the radiosensitivity of malignant tumors by inducing apoptosis." (PMID 32733808, 2020). "In cancer cells with a low Warburg effect, STAT3 is constitutively acetylated and undergoes steady-state translocation into the mitochondria, where it is constitutively involved in energy metabolism." (PMID 33003453, 2020). "TrxR1 contributes to cancer survival and progression by maintaining STAT3 in the reduced state, thus allowing STAT3 to be phosphorylated at Tyr705 to guide dimerization and transcriptional activity." (PMID 33003453, 2020). "The results suggest that LY5 can be an effective agent in cancer patients with constitutive activation of STAT3, and represents a promising approach for overcoming drug resistance induced by feedback activation of STAT3." (PMID 32872659, 2020). "Although both the STAT3 and mTOR pathways play crucial roles in tumorigenesis, studies are underway to investigate cross‐talk between the two pathways in cancer cells." (PMID 32495998, 2020). "The volcano plots showed that more than one compound displayed a correlation coefficient higher than 0.3 with STAT3 expression in the 10 cancer cell lines types, respectively." (PMID 32486001, 2020). "ZEB1 enhances IL-6 release and activates STAT3, which results in an increased proliferation potential of cancer cells." (PMID 32488850, 2020). "STAT3 promotes tumourigenesis by enhancing inflammation, proliferation, invasion, and immunosuppression in cancer." (PMID 33126409, 2020). "Signal transducer and activator of transcription 3 (STAT3) are considered one of the most common oncogenes in human cancers with a key role in GC progression." (PMID 33082325, 2020). "The present review focused on revealing the downstream and upstream mediators of STAT3 in GC cells to pave the way to understanding the oncogene pathways in this malignant tumor." (PMID 32545648, 2020). "Previous study demonstrated the importance of STAT3 in promoting chemoresistance of cancer cells via transcriptional regulation." (PMID 32298237, 2020). "Collectively, our findings indicate that the anti-cancer activity of AT-I in CRC is associated with the induction of apoptosis and suppression of glycolysis in CRC cells, via the disruption of JAK2/STAT3 signaling." (PMID 32273843, 2020). "e is natural logarithm and when predicting cancers, P = p‐STAT3 × 0.009138 + MSR1 × −0.005494 + Mcm2 × 0.133981 + (−0.654652)." (PMID 32860339, 2020). "Phosphorylated STAT3 can dimerize and translocate to the nucleus, where it acts directly on the promoter of PD-L1 to increase PD-L1 expression in human cancer cells." (PMID 32483468, 2020). "The relation between inflammation and cancer progression has been well established has reported that STAT3 is the major inflammation-promoting transcription factor shown to play important roles in cancer progression in various types of tumors." (PMID 32102537, 2020). "Andrographolide can stifle both constitutively activated and IL-6-induced phosphorylation of STAT3 and, consequently, its nuclear translocation into cancer cells." (PMID 32545187, 2020). "STAT3 promotes cancer stem cell self-renewal and metastasis and plays an important role in carcinogenesis." (PMID 33050000, 2020).
cancer (continued). "Among the STAT variants, STAT3 and STAT5 are well-studied in cancer relevance and frequently observed to undergo constitutive activation in several human cancers." (PMID 32967366, 2020). "STAT3-dependent gene expression in cancer is heterogeneous, reflecting the implication of this factor in multiple steps of the oncogenic program." (PMID 31947710, 2020). "Selective knockout of the STAT3 gene will block the transduction of related signalling pathways in cancer treatment." (PMID 32382281, 2020). "While STAT1 and STAT2 primarily drive immune signalling initiated by interferons, STAT3 and STAT5 have widely been linked to the survival and proliferative potential of a number of cancers." (PMID 32899142, 2020). "These complexities, together with the fact that the STAT3 signaling pathway is responsive to a great variety of cellular stresses and stimuli, pose difficulties in our understanding of abnormal hyperactivated STAT3 in cancers." (PMID 32972405, 2020). "In conclusion, the present study is the first report that G721-0282 shows anti-cancer activity in vitro and in vivo in OS by inhibiting the STAT3 pathway." (PMID 31929760, 2020). "The Src or STAT3 pathways are the attractive targets for anticancer therapy, thus Src kinase inhibitors or direct STAT3 inhibitors were shown to constrain cell proliferation and induce apoptosis in cancer cells." (PMID 32408543, 2020). "STAT3 gene knockdown or p-STAT3 inhibition activates the expression of pro-apoptosis proteins to mediate apoptosis of cancer cells." (PMID 32714202, 2020). "Recently, activation of transducer and activator of transcription 3 (STAT3) in NSCLC appeared as an alternative resistance mechanism allowing cancer cells to elude the EGFR signaling." (PMID 32438613, 2020). "For many years, STAT3 impact on cancer immunity was exclusively focused on its activity as a nuclear localized transcription factor." (PMID 33584695, 2020). "STAT3 signaling plays an important role in the maintenance and stemness of cancer stem cells, and its activation maintains ESCs in an undifferentiated state." (PMID 33634164, 2020). "Aberrant STAT3 activation in cancer cells mainly occurs through canonical signalling when activated receptor- or non-receptor tyrosine kinases phosphorylate STAT3 at the tyrosine (Y) 705 residue." (PMID 32231398, 2020). "Constitutive activation of STAT3 or NF-κB up-regulates major pro-inflammatory cytokines, such as TNFα, IL-1, and IL-6, which can promote cancer cell proliferation, angiogenesis, and metastasis." (PMID 33396715, 2020). "NANOGP8, the human-specific NANOG retrogene that is often expressed in human cancers, was also induced during reprogramming, to very low but detectable levels, in a STAT3-dependent manner." (PMID 32580970, 2020). "In later sections of this review, we will highlight a critical serine phosphorylation site on STAT3 in relation to cancer metabolism." (PMID 33003453, 2020). "FOXD2-AS1 acted as a scaffold for STAT3 and PRMT5, promoting STAT3 transcriptional activity, which is essential to maintain cancer stemness and facilitate chemotherapeutic resistance." (PMID 32848755, 2020). "STAT3 and its signal mediators are potential pharmacological and gene therapy targets and hold great promise for cancer therapy." (PMID 32222879, 2020). "The synthetic triterpenoid, CDDO-Imidazolide, which acts as an anti-inflammatory and anti-cancer drug, was demonstrated to suppress STAT3 and STAT5 phosphorylation and to induce apoptosis in MM cells." (PMID 31963765, 2020). "In cancer cells, the inhibition of TrxR1 expression results in increased oxidative stress and the accumulation of oxidized Prx2 and STAT3, which blocks STAT3-dependent transcription." (PMID 33003453, 2020).
cancer (continued). "Signal transducer and activator of transcription 3 (STAT3) is a transcription factor that contributes to cancer progression through multiple processes of cancer development, which makes it an attractive target for cancer therapy." (PMID 32422984, 2020). "Many of the targets have been well studied for their roles in cancer-induced muscle wasting, such as Stat3 and Fbox32." (PMID 33044689, 2020). "Coincidentally, the IL-6/STAT3 pathway was also involved in the process by which P. gingivalis and F. nucleatum promoted the proliferation of cancer cells." (PMID 33003438, 2020). "Correspondingly, suppressive monocytes from cancer patients show elevated levels of phosphorylated STAT3, and inhibition of STAT3 reverses the arginase-dependent immunosuppressive activity." (PMID 33042791, 2020). "Increasing evidence demonstrates that the STAT3 pathway is capable of the induction of EMT in cancer cells, and in this way, a number of upstream mediators, such as miR-449b-3p and SIX4, act as inducers of STAT3/EMT." (PMID 32545648, 2020). "In GC cells, the inhibition of STAT3 and YB-1 can suppress the resistance of cancer cells to chemotherapy." (PMID 32545648, 2020). "Previous studies have reported that activation of STAT3 or the IL-6-JAK-STAT3 signaling cascade in cancer cells promotes oncogenesis 52-55." (PMID 31938049, 2020). "This abnormal persistent STAT3 activation increases the cancer cell tolerance, prevents rejection of cancer by the immune system, reduces the effectiveness of immunotherapy and enhances the effectiveness of oncogenesis." (PMID 32863742, 2020). "The results of the present study revealed that FOXD2-AS1-promoted cancer stemness of LSCC cells relies on STAT3 transcriptional activation." (PMID 31959918, 2020). "The c-JUN/STAT3/PD-L1 axis is an important pathway in determining the immune evasion potential of cancer cells." (PMID 32855386, 2020). "The plant-derived natural compounds have demonstrated great potential in the regulation of the STAT3 signaling pathway in cancer therapy." (PMID 32545648, 2020). "As an oncogene, typically overexpressed in cancers, STAT3 regulates the expression of numerous downstream oncogenes including itself." (PMID 32331320, 2020). "STAT3 is a potential drug target for cancer therapy, and STAT3 phosphorylation inhibitor, Nifuroxazide can decrease the viability of multiple cancer." (PMID 33377648, 2020). "By adipocyte-derived molecules, STAT3 activity in cancer is also upregulated, leading to a significant drive in the survival mechanism." (PMID 32722030, 2020). "Numbers studies suggested that the interaction work mode of NF-κB and STAT3 was commonly existed in certain conditions, especially in cancer cells." (PMID 33041664, 2020). "Persistent activation of STAT3 has been well-documented in a broad range of human malignancies, including cancers of the lung, breast, ovary, colon, gastric, head and neck, pancreatic, and kidney." (PMID 32967366, 2020). "The use of STAT3 inhibitors for cancer treatment has been discussed in the literature for some time." (PMID 33330068, 2020). "Plenty of small molecule compounds have been approved in cancer prevention and therapy by inhibiting the activity of STAT3." (PMID 32486001, 2020). "In gastric cancer, the proliferation of cancer cells is inhibited by miR-135a via inactivation of JAK2/STAT3 and targeting cyclin D1, Bcl-xl40, kinesin family member C141 and the focal adhesion kinase (FAK) pathway." (PMID 32944391, 2020). "In cancers, hyperactivity of mTORC1/2 overlapped with the function of STAT3 especially in cell growth, survival, and migration, where STAT3 phosphorylation by mTORC1 is probably involved." (PMID 32495998, 2020).